VCAM1 (vascular cell adhesion molecule 1)
Diseases named in the same sentence as VCAM1 in open-access papers (continued):
Sharing a sentence is not in itself a finding about the gene and the disease.
leukemia (41 papers, 2010 to 2025). A malignant (clonal) hematologic disorder, involving hematopoietic stem cells and characterized by the presence of primitive or atypical myeloid or lymphoid cells in the bone marrow and the blood. "For instance, due to the extracellular matrix-vascular cell adhesion molecule-1 (VCAM-1) overexpression, BMSCs protect leukemia cells from cytotoxicity caused by cytarabine and etoposide treatment." (PMID 37554265, 2023). "In this study, we show for the first time that cordycepin disrupts leukemia-MSC association through downregulation of N-cadherin in leukemia cells and attenuation of leukemia-CM-induced VCAM-1, IL-6 and IL-8 in MSCs." (PMID 28266575, 2017). "The interaction of leukemia and stroma via VCAM-1/VLA-4 binding results in the bidirectional stimulation of nuclear factor kappa B (NF-kB) mediated molecular networks, which is necessary for the development of chemoresistance both in vitro and in vivo." (PMID 39994019, 2025). "Upon treatment with exosomes derived from leukemia cells, endothelial cells show increased expression of vascular cell adhesion molecule 1 (VCAM-1) and intercellular adhesion molecule 1 (ICAM-1), which have been associated with neovascularization." (PMID 37895415, 2023). "To assess the role of Vcam1 in the development of MLL‐AF9 leukemia, we then transduced Cas9 together with a vector or two independent Vcam1‐targeting single guide RNAs (sgRNAs) into mouse MLL‐AF9 cells." (PMID 36453131, 2023). "Flow cytometry analysis also confirmed the Vcam1 upregulation in FF‐10501‐01‐treated leukemia cells." (PMID 36453131, 2023). "In bone marrow samples from patients with primary acute myeloid leukemia, CD44 engagement by hyaluronan is involved in inducing the inside-out activation of integrin α4β1, thereby enhancing leukemia cell adhesion to vascular cell adhesion molecule-1 (VCAM-1)." (PMID 37932738, 2023). "Notably, both ICAM-1 and VCAM-1 protein levels were elevated in tumor-associated myeloid subsets relative to those in healthy littermate controls, which could contribute to the superior leukemia-supportive capabilities of tumor-associated myeloid cells." (PMID 37805579, 2023). "Accumulating new data implicate the VCAM-1/VLA-4 signaling axis as a potentially attractive therapeutic target in pediatric leukemias and solid tumors, which warrants additional preclinical and clinical development." (PMID 36497180, 2022). "Specifically, the interaction between the very late antigen 4 (VLA-4, integrin α4β1) in leukemia cells and vascular cell adhesion molecule 1 (VCAM-1) in endothelial cells is essential for lymphocytic leukemia cells to cross the BBB." (PMID 35256780, 2022). "In this study, we evaluated if cell adhesion to the molecule VCAM-1, which is present in the leukemia microenvironment, can favour the chemoresistance of T acute lymphoblastic leukemia (T-ALL)." (PMID 34298726, 2021). "M-MΦs secrete prosurvival factors, such as HGF, and EGF, and high levels of VCAM-1, which has been demonstrated to play an essential role in the BM stromal compartment in mediating leukemia cell chemoresistance." (PMID 34771453, 2021). "Cordycepin’s anti-leukemic effect in U937 and K562 cells was achieved through the reduced attachment of leukemia cells to MSC by decreasing N-cadherin expression on leukemia cells and vascular cell adhesion molecule-1 (VCAM-1) in MSCs." (PMID 33425742, 2020). "Expressions of N-cadherin in leukemia cells and VCAM-1 in MSCs were significantly impaired by cordycepin treatment." (PMID 28266575, 2017). "MSCs and leukemia cells were harvested and expression of VCAM-1 was examined by Q-PCR and Western blotting." (PMID 28266575, 2017). "Cordycepin has a profound effect on attenuating the expression of N-cadherin in leukemia and VCAM-1, IL-8 and Il-6 in MSCs." (PMID 28266575, 2017).
leukemia (continued). "Both CXCR4/SDF-1 and VLA-4/VCAM1 axes are involved in leukemia protection but little is known about the role of CCL2/CCR2 in AML biology and protection against chemotherapy." (PMID 28045930, 2017). "Cordycepin suppresses cell attachment of leukemia with MSCs and downregulates N-cadherin in leukemia and VCAM-1 in MSCs." (PMID 28266575, 2017). "Our findings indicate that co-culturing leukemia with MSCs induces N-cadherin expression in U937 cells and the incubation of MSCs with leukemic-CM (U937-CM and K562-CM) enhances VCAM-1 expression in MSCs." (PMID 28266575, 2017). "VCAM-1, which is constitutively expressed in bone marrow stromal cells, has been considered as a key protein that regulates the adhesion of α4β1-integrin (the receptor for VCAM-1) expressed by leukemia cells." (PMID 26652601, 2015). "Concordantly, the expression of surface proteins (CX3CR1, CXCR4, EMB, ITGB4, LSP, VCAM1) important for leukemia infiltration was downregulated in IGFBP2-null bone marrow AML cells." (PMID 24191913, 2013). "In MSC-leukemia co-cultures, VCAM-1 inhibitor could reestablish chemosensitivity to cytarabine and etoposide, indicating that targeting VLA-4/VCAM-1 may be a useful method to reduce stroma-mediated chemoresistance in B-ALL." (PMID 39994019, 2025). "Jacamo and colleagues demonstrated both in vitro and in vivo that leukemia-stroma interaction, through VCAM-1/VLA-4 binding, leads to the reciprocal activation of nuclear factor kappa B (NF-kB) mediated molecular pathways, necessary for mediating chemoresistance." (PMID 33922612, 2021). "We found that leukemia-CM may educate MSCs thereby inducing VCAM-1, IL-6, IL-8 and other effectors on promoting leukemia progression." (PMID 28266575, 2017). "It has recently been shown that the engagement of VCAM-1 (vascular cell adhesion molecule 1) on stromal cells with VLA-4 (very late antigen 4) on AML cells induces reciprocal NF-κB activation in leukemia and stromal cells and triggers stroma-mediated chemoresistance." (PMID 28561798, 2017). "Furthermore, VCAM-1/VLA-4 mediated leukemia-stromal interactions activate NFκB, which confers chemoresistance." (PMID 26956049, 2016). "In addition to anti-inflammatory activity, A. rugosa also has anti-fungal and anti-bacterial effects and it inhibits cytokine-induced vascular cell adhesion molecule-1 in human umbilical vein endothelial cells and apoptosis in leukemia cells." (PMID 25978436, 2015). "We demonstrated with an in vitro transendothelial cell migration assay that the treatment of HUVECs with LAMA84 exosomes induces LAMA84 migration through endothelial monolayer, likely due to a decrease of VCAM1-mediated adhesion of leukemia cells to EC and a concomitant chemotaxis toward serum." (PMID 25015105, 2014). "However, our own data show contributory roles of both ligands for chemoresistance of leukemia cells (and most strongly for VCAM1) at least in vitro, so that the situation currently remains unresolved." (PMID 24904821, 2014). "In addition, it has been demonstrated that CA4P, a novel tubulin-destabilizing agent, reduced the interaction of leukemia cells with neovessels by downregulating the expression of the adhesion molecule VCAM-1, thereby increasing leukemia cell death." (PMID 24137178, 2013). "Interestingly, nilotinib treatment upregulated E-selectin, ICAM-1, and VCAM-1 expression on human endothelial cells, which may result in the increased adherence of leukemia cells to E-selectin and the evasion of chemotherapy-induced cytotoxicity." (PMID 33425742, 2020). "We examined whether cordycepin regulates VCAM-1/VLA-4 expression in leukemia-stromal cells." (PMID 28266575, 2017). "We found both Vcam1 and, as previously highlighted, Fn1 and its antagonist Fbln1, to be higher abundant in FLEF relative to BMEF, suggesting a stronger impact of VLA-4/Vcam1 and VLA-4/Fn1 interactions in fetal-origin leukemia." (PMID 38555405, 2024).
leukemia (continued). "The expression of VCAM1, VEGFA, PECAM1, and ICAM1, which promote leukemia cells to cross the BBB, was studied by RT-PCR." (PMID 35256780, 2022). "We examined the expression of VCAM-1 and ICAM-1 in the marrow vascular niche of normal and ICN1 leukemia mice." (PMID 35401837, 2022). "We found that VCAM-1 and ICAM-1 were expressed in normal bone marrow ECs, but mice engrafted with ICN1 leukemia exhibited increased expression of both adhesion molecules." (PMID 35401837, 2022). "NALM-6 leukemia cells were then cultured with the endothelial monolayer to determine if their adhesive abilities were mediated by raised ICAM-1 and VCAM-1 expression in SPINK1-treated HUVECs." (PMID 35194087, 2022). "The VCAM-1/VLA-4 axis triggers NFκB activation and its consequent signaling which regulates cross-talk between leukemia and stromal cells." (PMID 28266575, 2017). "In the T leukaemia cell line Molt-4, overexpression of EWI-2 markedly impaired spreading and ruffling on VCAM-1." (PMID 20574531, 2010). "To investigate if the adhesion between leukemia cells and ECs induces EC UPR response and PERK activation, we blocked the ligands of ICAM-1 and VCAM-1 and found that PERK, eIF2a, and JAG1 activation was modestly attenuated by blocking LFA-1 but largely unaffected by blocking VLA-4." (PMID 35401837, 2022). "BMSCs can protect leukemia cells against chemotherapy drugs through various cytokines or growth factors (e.g., PDGF, VEGF, EGF, SCF, etc.)or cell-cell surface contact (e.g., SDF1/CXCR4, VLA4/VCAM1, CD44/E-selectin, etc.)." (PMID 34307365, 2021). "The inhibition of VLA‐4/VCAM‐1 interactions using anti‐VLA‐4 antibodies, and the blockade of Notch signalling pathway by using a γ‐secretase inhibitor partially restored chemotherapy sensitivity of leukaemia cells." (PMID 32686161, 2020). "Therefore, along with other recent data, our results suggest that modulating the interaction between VCAM-1 and VLA-4 in BM niches provides potential strategies to develop HSPC mobilizing agents or anti-leukemia drugs." (PMID 31375680, 2019). "However, treatment of CML mice with a monoclonal VCAM-1 blocking antibody did not reduce leukemia burden or numbers of LSCs in the spleen." (PMID 36163264, 2022). "Consequently, vascular cell adhesion molecule 1 (VCAM-1), derived from the mesenchymal stem cell membrane (173.8 ± 46.4 nm in thickness) on nanofibrils (1.0 ± 0.2 μm in diameter and 22.0 ± 10.1 μm in length), bound to integrin α4 (VLA-4) on the surface of leukemia stem cells." (PMID 40006568, 2025). "Furthermore, VCAM-1 blocking antibodies were also able to restore chemosensitivity to cytarabine and etoposide in MSC-leukemia co-cultures, suggesting that NF-kB or VLA-4/VCAM-1 targeting could be a clinically relevant mechanism to overcome stroma-mediated chemoresistance in B-ALL." (PMID 33922612, 2021). "Indeed, direct leukemia-MSC contact via VCAM-1/VLA-4 interactions, together with CXCL12/CXCR4 signaling and inflammatory cytokine signaling, may contribute, to a different extent, based on space and time, to enhance leukemia survival by activating NF-kB signaling within the leukemic BM niche." (PMID 33922612, 2021).
myocardial infarction (40 papers, 2011 to 2026). Gross necrosis of the myocardium, as a result of interruption of the blood supply to the area, as in coronary thrombosis. "These products, 2PY, 4PY, and VCAM-1, are all associated with residual cardiovascular event risk and linked to risk of myocardial infarction (MI), stroke, and death." (PMID 40699799, 2025). "The upregulated expression of VCAM-1 is considered to be a risk factor for plaque instability and myocardial infarction." (PMID 34320932, 2021). "VCAM1 expression levels are significantly increased in patients with HF caused by acute myocardial infarction compared with healthy controls, and VCAM1 levels have good predictive value for patient prognosis." (PMID 34593936, 2021). "Furthermore, endothelial expression of leukocyte-recruiting cell surface proteins like ICAM-1 und VCAM-1 is enhanced in Stamp2 deficiency, a mechanism which has been closely linked to myocardial infarct healing und -function." (PMID 34691017, 2021). "Reduced levels of N and VCAM-1 in GCF after periodontal disease therapy could reduce the risk of myocardial infarction in systemically healthy patients with periodontal disease." (PMID 29641752, 2018). "In previous studies, the anti-inflammatory effects of chokeberry, expressed as a reduction in inflammatory markers such as C-reactive protein (CRP), IL-6, and VCAM-1, were observed in post-myocardial infarction patients taking chokeberry extract." (PMID 39859963, 2024). "The endothelial cells in the blood vessels of the heart produce adhesion molecules, such as vascular cell adhesion molecule 1 (VCAM-1) and selectins, soon after myocardial infarction (MI) within minutes." (PMID 36658641, 2023). "Acute myocardial infarction and other coronary syndromes have been linked to ICAM-1 and VCAM-1 in several investigations." (PMID 36408439, 2022). "This study aimed to evaluate effects of periodontal treatment on GCF levels of neopterin and VCAM-1 in patients with chronic periodontitis (CP) with acute myocardial infarction (AMI) compared with systemically healthy CP patients." (PMID 29641752, 2018). "VCAM-1 expression in infarct tissue homogenates confirm that VCAM-1 expression is less pronounced as compared to histological findings yet significantly upregulated in the sub-acute phase after reperfused myocardial infarction in a transient matter." (PMID 28628621, 2017). "Having observed increases in both VCAM-1 and leukocyte infiltration in the kidneys, we next sought to investigate the effects of myocardial infarction on mRNA for other inflammatory mediators." (PMID 23471223, 2013). "We normalized the expression of Nppb and Vcam1, using different reference gene strategies and demonstrated that their induction after myocardial infarction was most clearly revealed with the optimal reference gene combination." (PMID 21858224, 2011). "However, previous data demonstrated that VCAM-1 serum levels assessed in patients with myocardial infarction who were brought to the emergency department were excellent indicators of heart failure after ACS." (PMID 40599142, 2025). "Similarly, male EH-WS mice also have increased expression of IL-6 and Vcam-1 in the aorta, which have been shown to be predictive of peripheral atherosclerosis progression and acute myocardial infarctions." (PMID 38659910, 2024). "Since GXNI treatment of acute myocardial infarction is mainly related to the anti-inflammatory effects mediated by CXCR1-NF-κB-COX-2/ICAM-1/VCAM-1-mediated IL-8 signaling pathway, the release of inflammatory factors and leukocyte infiltration were further examined." (PMID 36325326, 2022). "Spleen EC-derived VCAM1+- EVs mobilize splenic monocytes in myocardial infarction (MI)." (PMID 35681540, 2022).
myocardial infarction (continued). "In conclusion, the combination of transcriptome analysis and subsequent RT-PCR, WB and IHC verification revealed that GXNI has a significant therapeutic effect on acute myocardial infarction in mice mainly via inhibiting the CXCR1-NF-κB-COX-2/ICAM-1/VCAM-1 pathway." (PMID 36325326, 2022). "In fact, not only are VCAM-1 and ICAM-1 highly expressed on the endothelium overlaying atherosclerotic lesions, but an increased serum concentration of these molecules is also related to CV risk factors and incident myocardial infarction." (PMID 22962622, 2012). "For CVD, elevated levels of VCAM-1 have been reported to be associated with future cardiovascular mortality in CAD patients, and for patients with STEMI, VCAM-1 predicts post-STEMI heart failure and is associated with the development of new post-acute myocardial infarction heart failure symptoms." (PMID 39830114, 2024). "Endothelial cell activation and VCAM-1 expression also signal across-organ deployment of immune cells from remote reservoirs, such as the spleen, following acute myocardial infarction (MI) via endothelial cell-derived extracellular vesicles (EC-EVs)." (PMID 39698414, 2024). "Therefore, ICAM-1 and VCAM-1 are related with the progression of myocardial infarction." (PMID 36408439, 2022). "The FAM5C gene has been associated with myocardial infarction and functional studies have shown that it increases the production of ROS, nuclear factor-kappaB (NF-κB) activity, and expression of the intercellular and vascular cell adhesion molecules, ICAM-1 and VCAM-1." (PMID 29206233, 2017). "In all cases of myocardial infarction, median serum levels of hs-CRP, IL-6, NF-κB, TNF-α and VCAM-1 were 1.31 mg/L, 11.88 pg/ml, 11.34 ng/ml, 2.19 pg/ml and 1157.37 ng/ml, respectively." (PMID 39351476, 2024). "VCAM-1 supports angiogenesis, EDNRA mediates induction of CDH2 and VEGF by EDN, thereby contributing to tissue restoration after myocardial infarction, while BMPER is known to play an important role in osteogenesis." (PMID 37686058, 2023). "IL-6, VCAM-1, and ICAM-1 serum levels were assessed in patients with myocardial infarction who were brought to the emergency." (PMID 36408439, 2022). "The present study aimed to demonstrate the critical role of a specific population of CFs expressing vascular cell adhesion molecule 1 (VCAM1; VCFs) in the restoration of cardiac function in heart failure following myocardial infarction." (PMID 32936824, 2020). "AMI: acute myocardial infarction; CRP: C-reactive protein; IL-6: interleukin-6; VCAM-1: vascular cell adhesion molecule 1; ICAM-1: intercellular adhesion molecule-1; ACEi: angiotensin-converting enzyme inhibitors; ARBs: angiotensin II receptor blockers." (PMID 31778438, 2019). "Moreover, aronia berry extract has been shown to reduce blood cardiovascular risk markers such as oxidized-low-density lipoproteins (LDL), C-reactive protein (CRP), IL-6, soluble-ICAM-1, soluble-VCAM-1, and MCP-1 in patients after myocardial infarction." (PMID 31452653, 2019). "For example, transplanted cardiac progenitor cells that express VCAM-1 can activate the AKT, ERK and p38 MAPK signaling pathways and consequently prevent oxidative stress-induced cardiomyocyte death, eventually attenuating cardiac remodeling and dysfunction after myocardial infarction." (PMID 36467095, 2022). "Immunofluorescence showed that VCAM-1 was not expressed under basal conditions but was upregulated and clearly localised to glomeruli in mice with myocardial infarction and to the same cells expressing PECAM-1, indicating upregulation by glomerular endothelial cells." (PMID 23471223, 2013).